DNAJB6 (DnaJ heat shock protein family (Hsp40) member B6)
Description:
Has a stimulatory effect on the ATPase activity of HSP70 in a dose-dependent and time-dependent manner and hence acts as a co-chaperone of HSP70. Plays an indispensable role in the organization of KRT8/KRT18 filaments. Acts as an endogenous molecular chaperone for neuronal proteins including huntingtin. Suppresses aggregation and toxicity of polyglutamine-containing, aggregation-prone proteins. Also reduces cellular toxicity and caspase-3 activity. [Isoform B]: Isoform B but not isoform A inhibits huntingtin aggregation.
Synonyms: HSJ-2; HSJ2; MRJ; DJ4; DnaJ; HHDJ1; LGMD1D; LGMD1E; LGMDD1; MSJ-1
Tractability: PROTAC: ubiquitination databases record sites on it; its protein half-life has been measured.
Gene: Protein-coding gene on chromosome 7 (157,335,381 to 157,417,440, forward strand). Ensembl gene ENSG00000105993.
Subcellular location: Cytoplasm, perinuclear region; Nucleus; Cytoplasm, myofibril, sarcomere, Z line
Subcellular location (Human Protein Atlas): Nucleoplasm; Cytosol
Pathways (Reactome):
Cellular responses to stimuli: Attenuation phase; HSF1 activation; HSF1-dependent transactivation; Regulation of HSF1-mediated heat shock response
Gene Ontology:
Molecular function: ATPase activator activity; heat shock protein binding; protein binding; protein-folding chaperone binding; protein folding chaperone; DNA binding; Hsp70 protein binding
Biological process: intermediate filament organization; negative regulation of inclusion body assembly; nervous system process; protein folding; regulation of protein localization; regulation of cellular response to heat
Cellular component: cytosol; membrane; nucleoplasm; nucleus; perinuclear region of cytoplasm; Z disc; cytoplasm
Genetic constraint (gnomAD): Loss-of-function variants: 16 observed, 26.42 expected, observed/expected ratio (o/e) 0.61, 90% interval 0.41 to 0.92. The upper end of that interval is the gene's LOEUF score, 0.92, which puts it in group 3 of 6, group 1 being the genes least tolerant of losing a copy. Missense variants: 285 observed, 289.19 expected, observed/expected ratio (o/e) 0.99, 90% interval 0.89 to 1.09. Synonymous variants: 134 observed, 121.87 expected, observed/expected ratio (o/e) 1.1, 90% interval 0.95 to 1.27.
Gene-disease validity (ClinGen):
ClinGen rates the evidence that DNAJB6 causes each of these diseases.
muscular dystrophy, limb-girdle, autosomal dominant (autosomal dominant): Definitive. Autosomal dominant form of limb-girdle muscular dystrophy.
Homologues: Orthologues: macaque DNAJB6 (97% identical), chimpanzee DNAJB6 (93% identical), rat Dnajb6 (87% identical), mouse Dnajb6 (86% identical), dog DNAJB6 (85% identical), pig DNAJB6 (80% identical), tropical clawed frog dnajb6 (70% identical), rat Dnajb6-ps10 (67% identical), Drosophila melanogaster CG5001 (29% identical), Drosophila melanogaster DnaJ-1 (27% identical), Drosophila melanogaster CG2887 (26% identical), Caenorhabditis elegans dnj-26 (20% identical), and 3 more. Paralogues in human: DNAJB7 (55% identical), DNAJB2 (48% identical), DNAJB8 (45% identical), DNAJB4 (32% identical), DNAJB5 (30% identical), DNAJB1 (30% identical), DNAJB11 (27% identical), DNAJB13 (25% identical), DNAJB12 (23% identical), DNAJB14 (22% identical), DNAJB9 (22% identical).
Diseases named in the same sentence as DNAJB6 in open-access papers:
DNAJB6 is named in the same sentence as 88 diseases in open-access papers, as found by Europe PMC text mining. Sharing a sentence is not in itself a finding about the gene and the disease. The quoted sentences say what the papers report.
breast carcinoma (16 papers, 2008 to 2024). "Overexpression of miR-632 is significantly linked to reduced DNAJB6 protein expression, promoting invasiveness of breast cancer cells concomitant with increased expression of mesenchymal proteins such as ZEB2 and Slug and reduced expression of E-cadherin." (PMID 36499297, 2022). "Overexpression of micro-RNA-632 can downregulate DNAJB6 expression and substantially increase the invasive ability of breast cancer cells." (PMID 39335495, 2024). "In the relevant literature, it has been reported that miR-632 targets the human DnaJ/Hsp40 family member B6 (DNAJB6) in breast cancer." (PMID 37894814, 2023). "Parallelly, DNAJB6 overexpression can induce the degradation of β-catenin and suppress Wnt/β-catenin signaling in breast cancer and melanoma cells." (PMID 36499297, 2022). "A novel intronic lncRNA, lnc005620, whose host gene was DnajB6, a negative regulator of breast cancer, was discovered using RNA sequencing analysis." (PMID 33747911, 2021). "For example, RALY and SNW1 stimulate exon 2 inclusion in PRMT1, promoting breast cancer invasiveness and CDK12 promote alternative last exon splicing of DNA damage genes ATM and DNAJB6 thereby increasing migration and invasiveness of breast cancer cells." (PMID 31666932, 2019). "Depletion of CDK12 in breast cancer cells resulted in accumulation of DNAJB6 long isoform, thereby decreasing the migration and invasion abilities of MDA-MB-231 cells." (PMID 31523177, 2019). "Our studies highlight the role of DNAJB6 isoform a, MRJ(L), as a negative regulator of tumor growth in breast cancer." (PMID 18328103, 2008). "Collectively, our data indicate an important role for a totally uncharacterized isoform of DNAJB6 in breast cancer." (PMID 18328103, 2008). "The protein level of DNAJB6 was decreased with the aggressiveness of breast cancer cells." (PMID 38255948, 2024). "It has been found that DNAJB6 negatively affected cancer properties, and a loss of DNAJB6 would lead to tumor growth, epithelial–mesenchymal transition (EMT), and metastasis by aberrantly activating Wnt/β-catenin signaling during breast cancer progression." (PMID 38255948, 2024). "Moreover, DNAJB6 has been suggested to have a protective role against the epithelial-to-mesenchymal transition (Emt) in breast cancer." (PMID 37894814, 2023). "A previous study had established DNAJB6 as a gene target for miR-632 in human breast cancer." (PMID 37894814, 2023). "Therefore, a novel regulatory loop of β-catenin, MSX1, and DKK1 involving DNAJB6 represents the aberrant expression of DNAJB6 causing tumor growth, EMT, and metastasis of breast cancer." (PMID 36499297, 2022). "However, the expression levels of DNAJB4 and DNAJB6 in 52 breast cancer cell lines were significantly elevated in aggressive TNBC cell lines compared with DNAJB9." (PMID 33966034, 2021). "However, in breast cancer cells, DNAJB6/MRJ inhibits cancer progression by binding to HSPA8 and inhibiting Wnt/β-catenin signaling and epithelial-mesenchymal transition (EMT)." (PMID 34948322, 2021). "As an intronic lncRNA, the host gene of lnc005620 is DnajB6, a negative regulator of breast cancer." (PMID 33747911, 2021). "For instance, in breast cancer cells, CDK12 overexpression led to altered alternative last exon splicing of a subset of genes and increased the invasiveness of a breast cancer cell line by decreasing the expression of the long isoform of DNAJB6 (Paculová and Kohoutek, 2017)." (PMID 31024625, 2019). "In addition, the expression levels of DNAJB4 and DNAJB6 showed no significant influence on the OS and DMFS of patients with breast cancer." (PMID 33966034, 2021).
limb-girdle muscular dystrophy (14 papers, 2014 to 2024). Limb-girdle muscular dystrophy (LGMD) is a heterogeneous group of muscular dystrophies characterized by proximal weakness affecting the pelvic and shoulder girdles. "Intriguingly, recessive mutation in DNAJB6 causes limb-girdle muscular dystrophy due to defected chaperone function in the protein." (PMID 37817804, 2023). "Like several members of the CASA complex, mutation in DNAJB6 has been identified in human diseases linked to aberrant protein aggregation, like Limb-girdle muscular dystrophies (LGMDs)." (PMID 31427919, 2019). "Interestingly, a mutation in DNAJB6 causes Limb-girdle muscular dystrophies (LGMDs), characterized by aggregates of DNAJB6 sequestering CASA complex proteins." (PMID 32792938, 2020). "Indeed, DNAJB6 mutations cause Limb-girdle muscular dystrophies (LGMDs) in which a less-effective anti-aggregation activity of DNAJB6 has been found." (PMID 28680390, 2017). "DNAJB6 mutations were first described in patients with dominant limb-girdle muscular dystrophy (LGMD)." (PMID 32093037, 2020). "The enhanced penetrance of the phenotype could result from further reduction in the levels of expression or function of the chaperones, inducing more severe damage that can lead to different chaperonopathies, such as mutations in DNAJB6 that cause limb-girdle muscular dystrophy." (PMID 25988162, 2014). "DNAJB6/MRJ is ubiquitously expressed but most abundantly localized within the brain and in muscle tissue, with mutations causing dominant limb-girdle muscular dystrophy." (PMID 35164882, 2022). "The fact that a mutation in DNAJB6 is associated with limb-girdle muscular dystrophy which in turn is accompanied by pathological TDP-43 aggregates, indicates a protective function of DNAJB6 against dysregulated TDP-43 SG formatio." (PMID 33132902, 2020).
Parkinson disease (8 papers, 2016 to 2024). A progressive degenerative disorder of the central nervous system characterized by loss of dopamine producing neurons in the substantia nigra and the presence of Lewy bodies in the substantia nigra and locus coeruleus. "In vivo, the T193A mutation is associated with altered α-synuclein homeostasis and Parkinson’s disease, indicating a possible correlation between DNAJB6 oligomerization and chaperone activity." (PMID 37797698, 2023). "DnaJB6 protects human cells, animals and yeast from toxicity caused by amyloids composed of Huntington’s-related polyglutamine, Parkinson’s-related α-synuclein, and ALS- associated TDP-43, and it cures yeast of endogenous prions (infectious amyloids)." (PMID 36552355, 2022). "The T193A mutation in the C‐terminal domain (CTD) of DNAJB6 reduces both chaperone self‐oligomerization and anti‐aggregation of client proteins, and has recently been linked to Parkinson's disease." (PMID 35247211, 2022). "DNAJB6 was also observed to be up-regulated in the astrocytes of Parkinson’s patients and help in suppressing α-Synuclein aggregation, suggesting an overall protective mechanism against aberrant aggregation of proteins causing neurodegeneration." (PMID 38648719, 2024). "In a previous study, we found that the short isoform of DNAJB6 (DNAJB6(S)) had been decreased in the striatum of a mouse model of Parkinson's disease (PD) induced by 1-methyl-4-phenyl-1,2,3,6-tetrahydropyridine (MPTP)." (PMID 28280525, 2017). "Human J-domain protein (JDP) DnaJB6 has a broad and potent activity that prevents formation of amyloid by polypeptides such as polyglutamine, A-beta, and alpha-synuclein, related to Huntington’s, Alzheimer’s, and Parkinson’s diseases, respectively." (PMID 36552355, 2022). "This suggests that DNAJB6 is a central and versatile player in PQC and thus attractive target in several neurodegenerative diseases including in Parkinson’s disease." (PMID 27713507, 2016).
Alzheimer disease (6 papers, 2015 to 2025). A progressive, neurodegenerative disease characterized by loss of function and death of nerve cells in several areas of the brain leading to loss of cognitive function such as memory and language. "We treated DnaJC7 and DnaJB6 KO cell lines with either recombinant tau fibrils or brain lysates from subjects with Alzheimer’s Disease (AD), Progressive Supranuclear Palsy (PSP), or Corticobasal Degeneration (CBD)." (PMID 36993367, 2023). "Finally, it has been shown that DNAJB6 can block aggregation of multiple additional amyloid proteins involved in Alzheimer's disease and other tauopathies as well." (PMID 40536953, 2025). "Understanding the precise molecular mechanisms through which DNAJB6 acts to process or stabilize misfolding proteins are of keen interest for this and other protein aggregation myopathies and for common neurological diseases, including Alzheimer’s disease and frontotemporal dementias." (PMID 26205529, 2015). "We treated DnaJC7 KO and DnaJB6 KO cell lines with either recombinant tau fibrils, DS tau strain cell lysates (DS1, -9, or -10), or brain lysates from subjects with Alzheimer’s disease (AD), progressive supranuclear palsy (PSP), or corticobasal degeneration (CBD)." (PMID 37387473, 2023).
cardiomyopathy (5 papers, 2013 to 2023). A disease of the heart muscle or myocardium proper. "In summary, the DNAJB6(L) was the first cardiomyopathy gene discovered from a mutagenesis screen in adult zebrafish." (PMID 33329049, 2020). "DNAJB6 and SORBS2 were identified as new candidate cardiomyopathy susceptibility genes, which were supported by evidence from sequencing data from human patients." (PMID 33329049, 2020). "Among this last group, 43 proteins correspond to myopathies including the recently described DNAJB6, 20 to cardiomyopathies, 17 to neuropathies, 8 to metabolic muscle diseases, 3 to excitation abnormalities and 8 to unclassified NMD." (PMID 23414517, 2013). "Interestingly, all three deleterious mutants identified from that approach, ANO5, DNAJB6(L), and SORBS2, were either causative or susceptibility genes for cardiomyopathies." (PMID 33329049, 2020).
muscular dystrophy (5 papers, 2019 to 2022). Muscular dystrophy (MD) refers to a group of more than 30 genetic diseases characterized by progressive weakness and degeneration of the skeletal muscles that control movement. "In particular, mutations in BAG3 (BAG family molecular chaperone regulator 3), CRYAB (α-crystallin B chain), and DNAJB6 (DnaJ homolog subfamily B member 6) are known to cause individual forms of muscular dystrophy." (PMID 32823799, 2020). "DNAJB proteins are implicated in neuropathy (DNAJB2), muscular dystrophy or atrophy (DNAJB5, DNAJB6/MRJ), and primary ciliary dyskinesia (DNAJB13)." (PMID 34948322, 2021). "For example, it identified a pathway connecting the source protein DNAJB6, a chaperone that is causal gene for limb-griddle muscular dystrophy, and the target gene COL1A2 that was shown to be upregulated in muscular dystrophy patients." (PMID 31114913, 2019).
ovarian carcinoma (5 papers, 2019 to 2025). A malignant neoplasm originating from the surface ovarian epithelium. "Our findings demonstrated that circPLEKHM3 functions as a tumor suppressor in ovarian cancer cells by targeting the miR-9/BRCA1/DNAJB6/KLF4/AKT1 axis and may be used as a prognostic indicator and therapeutic target in ovarian cancer patients." (PMID 31623606, 2019). "Taken together, our data revealed that circPLEKHM3 inactivates the AKT1 and canonical Wnt/β-catenin signaling pathways by regulating the expression of BRCA1, DNAJB6 and KLF4 in ovarian cancer cells." (PMID 31623606, 2019).
myofibrillar myopathy (4 papers, 2016 to 2020). "Autosomal-dominant-subtypes were less common with 3 laminopathies (EDMD2; 3%), 1 myotilinopathy (Myofibrillar Myopathy; 1%), and 1 HSP40-proteinopathy (LGMDD1 DNAJB6-related; 1%)." (PMID 33250842, 2020).
colon cancer (3 papers, 2023 to 2024). "In colon cancer cells, DNAJB6 promotes cell adhesion, migration, and invasion through stabilizing the urokinase plasminogen activator receptor (uPAR), as well as activating many signaling transduction proteins through phosphorylation, including FAK, ERK1/2, and AKT." (PMID 39451243, 2024).
esophageal squamous cell carcinoma (3 papers, 2022 to 2024). Esophageal squamous cell carcinoma (ESCC) is a type of esophageal carcinoma (EC) that can affect any part of the esophagus, but is usually located in the upper or middle third. "DNAJB6 was found to promote ferroptosis and to serve as a protective factor in esophageal squamous cell carcinoma tissue." (PMID 36851083, 2023). "In concordance with the suppressive role of DNAJB6 in cancer metastasis, high nuclear DNAJB6 expression levels are inversely correlated with outcomes in esophageal squamous cell carcinoma (ESCC) patients." (PMID 36499297, 2022).
frontotemporal dementia (3 papers, 2015 to 2025). Frontotemporal dementia (FTD) comprises a group of neurodegenerative disorders, characterized by progressive changes in behavior, executive dysfunction and language impairment, as a result of degeneration of the medial prefrontal and frontoinsular cortices. "We show that DNAJB6 modifies the toxicity and solubility of multiple amyotrophic lateral sclerosis and frontotemporal dementia (ALS/FTD)-linked RNA-binding proteins (RBPs)." (PMID 41271702, 2025).
HIV-1 infection (3 papers, 2014 to 2024). The type species of lentivirus and the etiologic agent of acquired immunodeficiency syndrome (AIDS). "Additionally, during the early phases of HIV-1 infection, the former isoforms exhibit a significant increase, except DNAJB6, which later declined in the peak and late phase of infection." (PMID 39308823, 2024). "Prompted by the notion that DNAJ is a heat shock protein which may contribute to HIV-1 replication, we investigated the expression of DNAJB6 in lymphocytes and monocyte-derived macrophages (MDMs) which are considered the major targets of early HIV-1 infection." (PMID 26137520, 2014).
Huntington disease (3 papers, 2022 to 2023). Huntington disease (HD) is a rare neurodegenerative disorder of the central nervous system characterized by unwanted choreatic movements, behavioral and psychiatric disturbances and dementia. "In cellular and mouse models of Huntington’s disease, DnaJB2 and DnaJB6 reduce mutant Huntingtin aggregation and delay the onset of Huntington’s disease, whereas other JDPs do not significantly suppress aggregation." (PMID 36581212, 2023).
limb-girdle muscular dystrophy type 1D (3 papers, 2014 to 2022). "Historically, mutations within the DNAJB6 G/F domain have been associated with Limb-Girdle Muscular Dystrophy type 1D, now referred to as LGMDD1, a dominantly inherited degenerative disease." (PMID 32497100, 2020). "Mutations in DNAJB6, all of which map to a glycine-phenylalanine-rich region, are associated with limb-girdle muscular dystrophy type 1D (LGMD1D)." (PMID 24719117, 2014). "DNAJB6 was identified as the causative gene of limb-girdle muscular dystrophy type 1D." (PMID 35812750, 2022).
lymph node metastasis (3 papers, 2021 to 2024). "The nuclear expression level of DNAJB6 is negatively correlated with lymph node metastasis and poor prognosis in patients with ESCC." (PMID 39335495, 2024). "For instance, the level of DnaJ/Hsp40 homolog, subfamily B, member 6 (DNAJB6) in patients with EC is negatively correlated with lymph node metastasis." (PMID 35999642, 2022). "At the same time, lymph node metastasis was more common in ESCC patients with low DNAJB6 levels than patients with high DNAJB6 levels." (PMID 35999642, 2022). "Another study found that DNAJB6 level was negative related to lymph node metastasis in ESCC patient." (PMID 34764976, 2021).